CCR7 (C-C motif chemokine receptor 7)
Diseases named in the same sentence as CCR7 in open-access papers (continued):
Sharing a sentence is not in itself a finding about the gene and the disease.
tumor (continued). "Two distinct cDC1 activation states are differentially associated with Cxcl9 and Il12b/Ccr7 expression, respectively, each localising to different regions of the tumour, with the Cxcl9+ cDC1s being enriched in the parenchyma while the Il12b+ cDC1s remain located at the edges." (PMID 40745918, 2025). "Tumor effector memory CD8 T cells demonstrated overexpression of CCR7, IL7R, and CXCR4, which are associated with a naïve-like T cell state and inversely associated with T cell polarization and effector T cell function, as well as TXNIP, which negatively regulates T cell proliferation." (PMID 40848148, 2025). "The extent of overlap between CXCL9/CXCL10‐expressing and CCR7‐expressing tumour‐associated cDC1s, whether they represent end‐states or steps along the activation process and whether they have different functions, remains unclear." (PMID 40745918, 2025). "Additionally, we found that stem‐like TCF1+ CD8+ T cells are enriched in tumour‐bordering regions in association with the Il12b/Ccr7‐expressing cDC1s, while effector CD8+ T cells were enriched in the parenchyma in proximity to Cxcl9+ cDC1s." (PMID 40745918, 2025). "Similarly, low expression of CCR7 is associated with favorable prognosis, as it inhibits tumor progression by regulating immune cell migration." (PMID 40517358, 2025). "Notably, scRNA-seq of B16-F10 tumours and their dLNs34 demonstrated the same tissue-associated heterogeneity in CCR7+ DCs." (PMID 38267413, 2024). "The current consensus is that CCL19 may be a biomarker for metastasis and is associated with tumor promotion, however, the impact of CCR7 signaling in the TME is conflicting because it is expressed on tumor cells and immune cells." (PMID 38786066, 2024). "Tumor-associated CD83 + CCR7 + LAMP3+ DCs were found to selectively express in tumor tissue." (PMID 39256364, 2024). "Indeed, myeloid cells associated with a favourable clinical response expressed transcripts associated with tumour-residing CCR7+ DCs, including CCR7, CD274, IL15, PVR and CD70." (PMID 38267413, 2024). "Furthermore, these immune cells in TME underwent transcriptional reprogramming, including CD8 + T subgroups of CCR7 + and IL7R+, as well as M2-like monocyte subgroups expressing tumor-associated signature genes, like CCR7, SGKI, and RPL31." (PMID 37221625, 2023). "In a third, follow-up study, the group surmised that CCR7 activation turned on the Notch1 signaling pathway with concomitant elevation of the cancer stem cell population and thus loss of CCR7 produced attenuated Notch1 responses, reduced stem cell numbers and slowed tumor formation and growth." (PMID 35203305, 2022). "With the adjustment based on purity, the correlation analysis in STAD revealed that DDR1 was closely linked to most of immune markers in various TIICs, such as CD3E of general T cells, CD86 of monocytes, CCL2 of tumor-associated macrophages (TAMs), and CCR7 of neutrophils." (PMID 35935941, 2022). "In this study, PTX treatment could delay tumour growth but increase the risk of tumour metastasis, but inhibition of CCR7 could decrease the PTX-induced migration of B16F10 cells." (PMID 35280672, 2022). "Together, these findings suggest different immune escape mechanisms in both subtypes of HL that may be related to the different expression profiles of CCR7 in tumor-associated cells and of CCR7 ligands in the surrounding tissue." (PMID 34778050, 2021). "This study also confirmed, in a large cohort of 130 T-ALL patients, the positive correlation between ZAP-70 and CCR7 expression and, importantly, high CCR7 expression in tumor cells from BM biopsies at diagnosis was associated with a significant 11-fold increased risk of CNS involvement." (PMID 34778050, 2021).
tumor (continued). "Whatever the underlying reasons for the upregulation of CCR7, in the majority of diseases that are reviewed here, all these events lead to increased numbers of functional receptors at the surface of the tumor cells, which endows them with an increased migratory capacity." (PMID 34778050, 2021). "In others, tumor-associated CCR7 expression can be unaltered, but may trigger different cellular functions." (PMID 34778050, 2021). "CCR7 loss in DCs leads to deficient lymph node T cell activation and will increase tumor outgrowth." (PMID 32746880, 2020). "In addition, previous research has revealed that tumor infiltration by T lymphocytes with increased CCR7 expression is associated with favorable outcome in cancer patients." (PMID 32228580, 2020). "Notably, the expression of CCR7 was strongly reduced in association with tumor progression in DN2 cells at both the transcript and protein levels while remaining unchanged in the DN1 and DN4 subsets (data not shown)." (PMID 32582141, 2020). "The association of CCR5 and CCR7 chemokine/chemokine receptor axis with poor prognosis in oral SCC needs future molecular research to study mechanisms that lead to tumor growth and progression, considering that immunohistochemical studies can only confirm statistical relationship." (PMID 31011147, 2019). "In human, CCR7 expression by tumor cells is associated with LN metastasis in several cancers." (PMID 31024552, 2019). "A stronger expression of the lymphoid homing marker CD62L and CCR7 on less differentiated T cells is associated with increased anti-tumor activity in preclinical models of ACT and might be beneficial for CART cells." (PMID 31835562, 2019). "CC chemokine receptor 7 (CCR7) is associated with lymphatic metastasis in certain types of tumours." (PMID 27009073, 2016). "This implies that CCR7-low tumor cells are more susceptible to TGF-β1-induced EMT." (PMID 26176983, 2015). "In a similar manner, induced expression or ectopic delivery of LTβR downstream mediators, CCL19 or CCL21, in the TME results in inhibition of tumor growth or complete rejection of established tumors associated with increased infiltration by CD3+CCR7+ T cells and/or DCs in a range of cancer models." (PMID 24348473, 2013). "Moreover, a recent study of patients with metastatic CRC indicated that tumor infiltration with CCR7+ T cells was associated with a more favorable prognosis." (PMID 23874342, 2013). "The FoxP3+ T cells in other tumor types were similarly deficient in expression of CCR7 and CD62L." (PMID 22292042, 2012). "Also CCR7 levels in cervical adenocarcinoma/squamous cells are associated with invasion of lymph nodes as well as tumor cell proliferation and survival." (PMID 20049170, 2010). "Interestingly, our data show that CCR7 is expressed primarily on the mononuclear infiltrate associated with the tumor and is only very rarely expressed by the tumor cells." (PMID 18215331, 2008). "Altogether, these data suggest time-associated maturation of cDCs in the TME towards a CCR7+ state, and importantly, antigen-charged activated DCs may reside in the tumour for several days despite the expression of genes involved in tumour egress, including CCR7." (PMID 38267413, 2024). "Meanwhile, CCL21/CCL19 attract CCR7 + T cells as well as other immune cells and alter the ectopic lymph node structure associated with cancer prognosis by co-localizing synaptic cells and T cells, thereby promoting immune activity in the tumor microenvironment (TME) leading to immune infiltration." (PMID 37864213, 2023). "Several studies have suggested that T cell priming in the tumor draining lymph node is required to mount anti-tumor immunity A study showed that tumor-associated cDC1 bearing intact tumor Ag traffic to the draining lymph node to prime naïve CTLs in a CCR7-dependent manner." (PMID 30809220, 2019).
tumor (continued). "Multivariate Cox analysis was further performed and suggested high CCR7 expression as an independent adverse prognostic factor for mRCC patients’ OS prediction (HR 2.256, 95% CI 1.336–3.809, P = 0.002; P = 0.003 after 1000 bootstrap), together with tumor histology and Heng’s risk group." (PMID 28114889, 2017). "We found that increased recruitment could be attributed to higher CCL22 production by EBVaGC cells, decreased emigration caused by downregulated lymphocyte homing receptor CCR7 on the Treg surface, higher Treg proliferation rates and lower apoptosis rates at tumour sites." (PMID 26673957, 2015). "A most recent report indicated that the low frequency of circulating CD8+ CCR7+ T cells is a significant risk factor for tumor recurrence in patients with head and neck cancer, suggesting that skewed distribution of functionally distinct CD8+ T-cell subset may occur during cancer progression." (PMID 24465587, 2014). "HPSE-pX-Δ1-30 CAR T-derived extracellular vesicles (EVs) retained CAR and chemokine receptors (CCR5/CCR7), carried apoptotic ligands, and were efficiently taken up by tumour cells and T cells." (PMID 42275439, 2026). "Chemokine networks, particularly the CXCL12/CXCR4/CCR7 axis, play a crucial role in guiding tumor cells to their destinations." (PMID 41596524, 2026). "The CCR7-CCL21 chemokine axis facilitates lymphatic dissemination, as CCL21 is continuously expressed by lymphatic endothelial cells and lymph node stromal cells, directing CCR7-expressing tumor cells towards lymphatic vessels and draining lymph nodes." (PMID 41596524, 2026). "cDC_LAMP3 expressed high levels of the chemokine receptor CCR7, suggesting that they are predestined for homing to tumor-draining lymph nodes." (PMID 40991399, 2026). "This study highlights the opposing effects of tumor cell-derived versus stromal cell-derived CCR7 expression and guides the precision treatment for HCC." (PMID 40685403, 2025). "To assess the influence of Mig DCs influx on anti-tumor efficacy, we employed α-CCR7 or isotype to block Mig DCs migration during CR108+OVA treatment." (PMID 40606756, 2025). "The data showed high expression of CCR7 in tumor cells predicted lower Overall Survival (OS) of patients and knocking out CCR7 enhanced the sensitivity of HCC to sorafenib as a result of inhibiting EMT through the AKT and ERK signaling pathways." (PMID 40685403, 2025). "Chemokine receptor engineering (CXCR1, CXCR4, CCR7) improves trafficking and tumor infiltration both in hematological and solid tumors." (PMID 41487532, 2025). "Tumor-derived TGF-β inhibits DC migration to dLNs by reducing CCR7 expression, and TGF-β neutralization via conventional or bispecific antibodies increases functional DC populations in the TME." (PMID 41430039, 2025). "Similar to what we observed in murine tumours, we identified a higher proportion of CCR7+ cDC1s located within 10 μm of the TCF1+ mask compared with CXCL9+ cDC1s." (PMID 40745918, 2025). "Lastly, analysis of a published spatial transcriptomic dataset of human tumours revealed that CCR7+ cDC1s, the human equivalent of the murine Il12b+ cDC1s, are also preferentially associated with TCF1+ T cells as compared with the CXCL9+ cDC1s." (PMID 40745918, 2025). "To further explore the capability of lenalidomide in suppressing DLBCL tumor growth via the CCR7/ERK1/2 axis in vivo, we conducted animal experiments." (PMID 39735670, 2025). "Treg cell depletion restored CD40 expression by CCR7+ DCs, enhanced immunostimulatory programs, and improved T cell-dependent tumor control." (PMID 41421339, 2025). "The activation of antitumor CD4+T cells upon adoptive transfer of tumor-specific Tc9s occurs as a result of IL-24 secretion and recruitment of CCR7+cDC2s (conventional type 2 DCs) into tumor-draining LNs, which prime host CD4+T cells against relapsing tumors." (PMID 41009359, 2025).
tumor (continued). "The precision regulation of CCR7 signal, for example blocking in tumor cells and boosting in immune cells, is expected to a promising therapeutic strategy for HCC." (PMID 40685403, 2025). "These cells were reminiscent of the cDC1 cellular state associated with tdLN migration, but also of CCR7+ cDC1s shown to sustain CD8+ T cells’ survival and proliferation within tumours." (PMID 40745918, 2025). "When we focused on the high infiltration of CCR7+ immune cells in tumor mesenchyme, we should give enough thought to the complicated TME of HCC." (PMID 40685403, 2025). "CCL19, the ligand of CCR7, was selected to target CCR7-positive tumor cells, an immunosuppressive and highly invasive cell population." (PMID 40089746, 2025). "A key axis is CCL21-CCR7, where lymphatic endothelial cells secrete CCL21 to attract CCR7+ tumor cells." (PMID 40904508, 2025). "Our study identified and validated the efficacy of SLC16A6, CCR7, and MS4A1 as tumor suppressors implicated in AML progression and related to immune cell infiltration." (PMID 41036204, 2025). "As the most potent APCs in the body, DCs upregulate the expression of costimulatory molecules such as CD80, CD86, CD40, and the chemokine receptor CCR7 upon stimulation with tumor antigens." (PMID 40040692, 2025). "A positive correlation was also found between CCR7 expression and tumor size (p < 0.001), TNM stage (p < 0.001) as well as Age (p = 0.002)." (PMID 40685403, 2025). "Simultaneously, we revealed CCR7 expression in stromal cells, with increased infiltration of CCR7+ immune cells into the tumor mesenchyme associated with high CCL21 expression at tumor sites." (PMID 40685403, 2025). "In tumors, DC and cDC1 that phagocytose apoptotic tumor cell fragments migrate to TDLNs in a CCR7-dependent manner, where they cross-present TA to CD8+ TRM cells to potentiate their expansion in TDLNs." (PMID 41194931, 2025). "We further analyzed the correlation between the OS of patients and the CCR7 expression in mesenchymal sites of tumor tissues." (PMID 40685403, 2025). "Those anti-tumor effects are mainly caused by the pathways of B cells, such as CCL19, -21/CCR7 axis and CXCL13/CXCR5 axis." (PMID 40158161, 2025). "On the other hand, the infiltration of CCR7+ immune cells in tumor mesenchyme was promoted by VEGF-C administration, which increased the efficacy of anti-PD-1 immunotherapy in HCC mouse models." (PMID 40685403, 2025). "A recent study using mouse models has revealed that VEGFC activates the CCL21/CCR7 signaling pathway, which promotes the activation and recruitment of naïve T cells to the tumor." (PMID 38980684, 2025). "CCR7 is widely expressed on diverse immune cells and certain tumor cells, serving as a critical regulator of lymphocyte migration to secondary lymphoid organs." (PMID 41445742, 2025). "Upregulation of CCR7 by tumour‐resident cDC1s and cDC2s can be accompanied by shared heterogeneous transcriptional activation programmes that are associated with the activation or suppression of T cell effector function." (PMID 40878038, 2025). "Intratumoural stem‐like CTLs located close to the tumour vasculature transition to a CXCR6hi effector‐like state by interacting with CCR7+ cDCs expressing CXCL16, as well as the cytokine IL‐15 that facilitates T cell survival and clonal expansion." (PMID 40878038, 2025). "Future research must focus on multiplexed editing using CRISPR/Cas9 to simultaneously manipulate several signaling pathways, including IL-12 secretion and CCR7 migratory receptor expression, to induce a robust immune response against the tumor." (PMID 41176596, 2025). "CCR7 expression is important for cDC migration to the tumour‐draining lymph node, but, interestingly, recent studies have suggested that CCR7+ cDCs can also remain in tumours and perform local functions." (PMID 40745918, 2025). "On the one hand, knocking out the expression of CCR7 in tumor cells through the CRISPR-cas9 system enhanced their sensitivity to sorafenib." (PMID 40685403, 2025).
tumor (continued). "In addition, the proportion of CD8+ T cells was expressed higher in OSCC tumor tissues from CCR7-deficient mice, suggesting that CCR7 may promote tumor growth by inhibiting the activation of initial CD8+ T cells, thereby affecting the proliferation and replenishment of antitumor immune CD8+ T cells." (PMID 41445742, 2025). "CCR7+ cDCs in tumours also produce IL‐12, which was shown to be important for reinvigorating the CD8+ T cell response during immune checkpoint blockade." (PMID 40745918, 2025). "In tumor cells, higher expression of CCR7 is related to lower OS of HCC patients, which makes CCR7 expression serve as an independent prognostic factor for HCC patients." (PMID 40685403, 2025). "Based on this, we analyzed the migration status of DCs (identified as CCR7+within the CD11c+ cells) in the tumor microenvironment." (PMID 40761260, 2025). "The results showed that ZNF439 and KDM5D were highly expressed in normal tissues, whereas KMO, FT57, HDAC9, GSAP, and CCR7 were highly expressed in tumor tissues." (PMID 40145017, 2025). "Although high expression of CCR7 in tumor cells is related to EMT and sorafenib resistance, however, a higher CCR7 expression was also found in mesenchymal sites in HCC, which was often involved in the infiltration of CCR7+ immune cells." (PMID 40685403, 2025). "Analysis of cDC1 heterogeneity in samples from cancer patients also reported the existence of CXCL9+ and CCR7+ cDC1s in human tumours." (PMID 40745918, 2025). "In contrast, CCR7–Cxcl9‐expressing cDC1s are preferentially found within the tumour parenchyma alongside effector CD8+ T cells." (PMID 40745918, 2025). "In this regard, we demonstrated that the CCR7→ CXCR3 switch was significantly decreased in RARα‐TG CTLs in tumor‐draining lymph nodes." (PMID 40068101, 2025). "To investigate the in vivo effects of CXCL14 knockdown or blockade of the CXCL14/CCR7/STAT3 axis within the tumor microenvironment (TME), we coinjected CAFs and T24 cells, each with different shRNAs, subcutaneously into nude mice." (PMID 40898244, 2025). "Analysis of the expression of the TILB-related signature genes in B Plasma cells showed that KMO, IFT57, HDAC9, GSAP, and CCR7 were significantly highly expressed in tumor tissue, while ZNF439 and KDM5D showed a similar trend." (PMID 40145017, 2025). "For the correlation between CCR7 expression and tumor size, one study reported a cut-off diameter of 3 cm, while the other studies (n = 11) reported a cut-off diameter of 2 cm." (PMID 40299690, 2025). "Mechanistically, this treatment approach enhances migration of activated CCR7+ dendritic cell surveillance across the tumor-sentinel lymph node axis, revealing a shift from their canonical role in promoting tolerance to driving antitumor immunity." (PMID 40675962, 2025). "This memory reprogramming was further supported by elevated CCR7 expression, a key mediator of T cell homeostasis, lymphoid homing, and sustained anti-tumor responses." (PMID 41372119, 2025). "In these scenarios, tumor cells often exhibit CCR7 positivity alongside increased extracellular matrix levels of CCL21, supporting enhanced migratory capacity mediated via the PI3K/Akt and mTOR signaling pathways." (PMID 40861461, 2025). "High expression of CC chemokine receptor 7 (CCR7) in tumor cells predicted lower Overall Survival (OS)." (PMID 40685403, 2025). "Although 4 Gy × 2 induced tumor rejection, the frequency of CCR7+ DCs trafficking to SLNs remained comparable to that observed with a single 4 Gy dose." (PMID 40675962, 2025). "In melanoma patients, CD141+ DCs, as the most migratory DC subpopulation, deliver tumor antigens to the TDLN via a CCR7-dependent pathway, and are a key cell type for initiating CD8+ T cell responses." (PMID 40904508, 2025). "It was shown that CCR7 expression was up-regulated both in the tumor sites and mesenchymal sites (Right)." (PMID 40685403, 2025).